WT1 (WT1 transcription factor)
Diseases named in the same sentence as WT1 in open-access papers (continued):
Sharing a sentence is not in itself a finding about the gene and the disease.
cancer (continued). "Loss of the transcription factor Wilms tumor 1 (WT1) has been correlated with decreased proliferation and increased cell senescence in KRAS driven cancer cell lines." (PMID 33777798, 2021). "We previously reported that several small double-stranded RNAs (dsRNAs) targeting the PRKC apoptosis WT1 regulator (PAWR) promoter can up-regulate PAWR gene expression effectively in human cancer cells." (PMID 34220332, 2021). "Only three mutations were in genes linked to cancer development: NF2 I174fs and MLL3 both detected in the LR-Om and characterized as pathogenic, and WT1 in the KR lesion." (PMID 34301805, 2021). "Other work in vitro analyzed that the 17AA (-)/KTS (-) WT1 isoform modulates the expression of cytoskeletal regulatory proteins such as α-actinin 1, cofilin, and gelsolin, allowing cancer cells to acquire a more aggressive phenotype." (PMID 34845427, 2021). "Additional target antigens were verified experimentally and included several cancer epitopes that are actively being pursued for cancer immunotherapy, namely WT1, MG50, Tyrosinase, gp100 and NY-ESO-1." (PMID 33836029, 2021). "The analysis of WT1 isoforms in other types of cancers highlighted that different cellular contexts can determine their transcriptional function." (PMID 32244895, 2020). "Regarding the impact of WT1 on the cancer patient prognosis most of the scientific studies have shown that positive expression of WT1 was linked with an unfavorable biological behavior." (PMID 32859123, 2020). "DC vaccines pulsed with WT1 peptides, synthesized artificially, were previously shown to be safe and feasible with few adverse reactions in patients with advanced cancer." (PMID 32231023, 2020). "Being overexpressed in a variety of hematologic malignancies and solid tumors, WT1 has been considered as a molecular target of cancer immunotherapy in several solid tumors and as a tool for monitoring minimal residual disease in leukemic patients." (PMID 32856872, 2020). "After the administration of WT1-DCs, immune monitoring demonstrated that WT1-DCs induce acquired immunity in patients with cancer." (PMID 32231023, 2020). "We divided TFs into three categories: the first one is represented by TFs whose splice variants affect the cancer cell phenotype by regulating different classes of genes (NF-YA, STAT3, TCF4 and WT1)." (PMID 32244895, 2020). "Accordingly, CLEC9A‐WT1 vaccines also hold the potential to enhance immunogenicity and response rates when combined with a variety of immunotherapies and standard treatments in patients with cancers that express WT1." (PMID 32547743, 2020). "Overexpression of WT1 partially prevents degrasyn‐induced anti‐cancer activity, suggesting that degrasyn presents strong anti‐metastasis via degrading WT1 protein." (PMID 31845546, 2020). "In detail, the activity of NF-YA, STAT3, TCF4 and WT1 isoforms in cancers has been documented and proposed for cancer molecular stratification." (PMID 32244895, 2020). "Further clinical studies using WT1-pre-pulsed DCs with OK-432 for patients with cancer would be needed to monitor the induction of IFN-γ producing WT1-CTLs as wells as to improve the immune environment in vivo." (PMID 32231023, 2020). "This technique allows the induction of multi-epitope T-cell responses, for example, in cancer patients following therapeutic vaccination with antigen-loaded DCs, such as the Wilms’ tumor 1 (WT1) protein." (PMID 31972992, 2020). "Data from the literature have also revealed that WT1 can promote invasion, migration and metastasis, facilitate angiogenesis and confer drug resistance to cancer cells." (PMID 32859123, 2020). "As a transcript factor, WT1 maintains the survival and metastasis of cancer cells through modulating series of important genes." (PMID 31845546, 2020).
cancer (continued). "In this study, we performed phenotypic and functional analyses on WT1-DCs pre-pulsed with WT1 peptides in low-adhesion culture maturation, and we evaluated active WT1-CTLs after WT1-DC administration in patients with cancer." (PMID 32231023, 2020). "Prospective clinical trials are required to evaluate the efficacy of acquired immunity in response to WT1-DC vaccination in large number of cancer patients." (PMID 32231023, 2020). "The acquisition of WT1-CTLs as a proof-of-concept drug delivery in vivo was observed in patients with cancer who received WT1-DCs vaccination." (PMID 32231023, 2020). "A clinical study revealed that WT1-specific CTLs (WT1-CTLs) were detected upon using the WT1-DCs vaccine in patients with cancer." (PMID 32231023, 2020). "The Wilms’ tumor 1 (WT1) gene encoding a zinc finger transcription factor plays an important role in normal urogenital development and cancer pathogenesis." (PMID 32580769, 2020). "WT1 is widely expressed by many human cancers and contains numerous CD4+ and CD8+ T‐cell epitopes distributed across multiple HLA allotypes." (PMID 32547743, 2020). "WT1 also affects cytoskeletal rearrangement and participates in cell movement by regulating actin activity, which indicated the possible role of WT1 in cancer cell invasion and migration." (PMID 32210734, 2020). "Vaccines that prime Wilms' tumor 1 (WT1)‐specific CD8+ T cells are attractive cancer immunotherapies." (PMID 32547743, 2020). "WT1 28z-CAR T cells showed WT1-HLA-A*02:01-specific cytotoxicity against various cancer cell lines, including MM." (PMID 30518815, 2019). "The frequency of WT1 overexpression in pediatric cancer patients appears to be lower than it is in adults." (PMID 31546858, 2019). "With the advancements of cancer immunology, several TAAs have been identified, and one of them is a WT1 product." (PMID 31245293, 2019). "Studies have reported that the WT1 protein, the gene product of WT1, is a promising target antigen for cancer vaccine therapy." (PMID 31029154, 2019). "This study demonstrates the therapeutic potentials of inhibiting HO-1 with SnMP to enhance antigen-specific T-cell responses in the treatment of cancer patients with WT1-positive disease." (PMID 30678050, 2019). "Chimeric antigen receptor (CAR)-T cells with antitumor activity have been developed by targeting processed surface peptides on cancer cells derived from the intracellular WT1 protein." (PMID 31058089, 2019). "CD8+ cytotoxic T-lymphocytes (CTLs) specific for WT1 occur in cancer patients as well as in low frequencies in healthy donors." (PMID 30678050, 2019). "It remains partly unclear why WT1-specific T cells are not only present in cancer patients, but also in healthy individuals." (PMID 30678050, 2019). "The top ranked gene, WT1, had an Oncoscore of 77.5 while 81 genes had Oncoscores ≥1, indicating at least one citation in a cancer-related article." (PMID 30866861, 2019). "In humans, peptide-based vaccines with HLA-A24-restricted WT1235−243 epitopes have been well characterized in the literature to elicit WT1-specific CD8+ T cell responses in adult and children cancer patients with the HLA-A24 allele." (PMID 30631324, 2018). "WT1 has recently been listed among the top of the 75 ideal cancer antigens in immunotherapies by the U.S. National Cancer Institute." (PMID 30631324, 2018). "Several recent early-phase anti-WT1 DC vaccine clinical trials in multiple cancer types reported a correlation between anti-WT1 CTL responses and clinical response, showing its potential as a therapeutic strategy." (PMID 29867960, 2018). "Wilms tumor 1 (WT1) is a particularly promising target for cancer vaccination because it is overexpressed in the majority of myeloid cancers and has an essential role in leukemogenesis." (PMID 29344432, 2018).
cancer (continued). "In Wt1+/− mutant cells, progenitors cannot respond to WNT9b induction and thus proliferate into nephrogenic rests that transform into malignant tumors upon wt1 ablation." (PMID 29623275, 2018). "WT1 has been listed among the top of the 75 ideal cancer antigens in immunotherapies by the U.S. National Cancer Institute." (PMID 30631324, 2018). "Subgroup analysis by cancer types revealed that WT1 overexpression had an unfavorable effect on OC in univariate model (metaHR = 2.51, 95% CI = 1.81–3.48)." (PMID 29995811, 2018). "WT1 is a transcription factor that is overexpressed in the cancer cells of most AML patients and can be measured in both bone marrow and peripheral blood samples." (PMID 29415891, 2018). "Owing to its specificity, oncogenicity, immunogenicity, and therapeutic function, WT1 has been classified as one of the most promising targets for cancer immunotherapy." (PMID 28176175, 2017). "T-cell receptor mimic antibodies have not yet entered the clinic, although Novartis have partnered with Eureka Therapeutics and Memorial Sloan Kettering Cancer Center to develop their ESK1 TCRm targeting WT1." (PMID 28868054, 2017). "Wilms’ tumor 1 (WT1) is a potential target antigen for cancer immunotherapy as it is over-expressed in the majority of solid tumors." (PMID 28176175, 2017). "Clinical trials of cancer vaccines using synthetic WT1 peptide have been conducted in patients with AML as well as with solid tumors for more than a decade and some clinical responses and benefits have been observed." (PMID 28321480, 2017). "Among the candidates, WT1 was selected for further study because it acts as an oncogene in human cancers." (PMID 29016617, 2017). "Our study sheds light on the potential of PCA from commonly used anti-cancer Chinese herbal Medicine SJC as a lead compound targeting WT1 in the discovery of anti-HCC drugs." (PMID 29285297, 2017). "Clinical efforts to date have focused on shared self-peptides that are from proteins upregulated in some cancers, such as WT1 antigen, differentiation antigens like gp100 and MART-1, and cancer/testis antigens like NY-ESO and MAGE-A3 (for example,10–16)." (PMID 27703664, 2016). "Despite an extensive search, only cancer-testes antigens and WT1 antigen have been recognized as T-cell epitopes in MDS." (PMID 27314337, 2016). "Our study is mainly focused on WT1 role in NB which represents the most common and malignant tumor of early childhood." (PMID 27014421, 2016). "Though proposed as a promising target antigen for cancer immunotherapy, the prognostic value of Wilms' tumor 1 (WT1) in solid tumors remains inconclusive." (PMID 25748047, 2015). "Because of its implications in the etiology of cancer, clinical values of WT1 expression are the subject of increasing scrutiny." (PMID 25748047, 2015). "WT1 specific responses analyzed by ELISpot assay were detected in 34 out of 46 cancer patients (73.9%) after seven pulsed DCs vaccinations of WT1 peptide." (PMID 28536414, 2015). "The Wilms’ tumour‐1 (WT1) protein is considered a prime target for cancer immunotherapy based on its presumptive immunogenicity and widespread expression across a variety of malignancies." (PMID 25882672, 2015). "As high expression of wild-type WT1 has been reported in cancer cells with oncogenesis, the modified WT1 peptide for HLA-A*24:02 has been proven to be more effective than HLA-A*02:01." (PMID 26690485, 2015). "Positive WT1 protein staining by IHC in cancer tissue specimens was found more frequently in advanced stages, grade 3 and serous OCs." (PMID 24715586, 2014). "The other tumor suppressor gene induced by TCPOBOP in cancer cells, WT1, was previously shown to be expressed at lower levels in fatal cases of NSCLC than in survival cases." (PMID 24959746, 2014). "In 2009, the cancer antigen prioritization project of the National Cancer Institute ranked Wilms tumor 1 (WT1) as the first antigen, followed by mucin 1, cell-surface associated (MUC1)." (PMID 25298213, 2014).
cancer (continued). "WT1 knockdown performed in different cancer lines showed to impede cell proliferation and viability by a multitude of mechanisms." (PMID 25474318, 2014). "Having confirmed the high expression of WT1 and AWT1 in myeloid derived cancer cell lines we next wished to determine if this expression profile was associated with lineage specific DNA methylation changes." (PMID 24405639, 2014). "Overexpression of WT1 has been demonstrated in various human cancers including acute leukemia, breast cancer, brain tumors, and other tumors 14–18." (PMID 24715586, 2014). "WT1 peptide-based immunotherapy will be a routine option for malignant tumor treatment in the near future." (PMID 25026998, 2014). "WT1 expression has been reported to be upregulated in a variety of solid tumors, including in ccRCC where it seems to act as an oncogene, yet little is known about the pathophysiological consequences of WT1 expression in cancer." (PMID 25025131, 2014). "For example, overexpression of HtrA2 substrates such as IAPs and the Wilms’s tumor suppressor protein WT1 in several cancers suggests modulation of HtrA2 protease activity can effectively regulate their relative levels in the cells." (PMID 23457469, 2013). "For example, aberrant alternative splicing of certain tumor suppressors, such as breast cancer 1 and 2 (BRCA1/2), Wilms tumor 1 (WT1), and adenomatous polyposis coli (APC), results in mutations that account for inherited and sporadic susceptibility to cancer." (PMID 23236423, 2012). "There is a growing number of studies developing anti-WT1 immune therapy for common cancers predicated on the belief that WT1 is expressed at high levels in cancers, but very low levels in the normal adult." (PMID 22216009, 2011). "For promoter-associated CpG islands, a number of them, including those of NTF3, FGF, OSR1, HOXA6, NPY and WT1, have previously been reported as differentially methylated in other cancer types." (PMID 20051947, 2010). "• Targets of WT1 are statistically enriched for cancer related functions including metastasis and apoptosis." (PMID 18564415, 2008). "The incorporation of a fluorine in a TcR binding position has generated a peptide that elicits a better immune response than the native sequence, which was able to recognize and kill WT1+ cancer cells." (PMID 19079589, 2008). "Wt1 is a transcription factor and has been found to be overexpressed in several types of cancers with poor prognosis." (PMID 18218118, 2008). "As a gene involved in modulating the cancer cell phenotype, WT1 has been found to regulate the expression of genes important in cell proliferation, differentiation and response to chemotherapy." (PMID 17634147, 2007). "On the basis of these findings, we performed a phase I clinical trial of a WT1 peptide cancer vaccine for the patients with malignant neoplasms." (PMID 17619750, 2007). "We found high expression levels of WT1 in pT3 stage carcinoma samples, and expression of wild-type WT1 mRNA in both advanced stages (≥ pT3) and HR stage LuCaP 23.1 carcinomas." (PMID 17137506, 2006). "Although the WT1 promoter region was significantly hypermethylated, two CpG sites located in Sp1 motifs were unmethylated in the majority of cases (68-74% of carcinomas)." (PMID 9365158, 1997). "WT1-specific immunotherapies, such as peptide vaccines, DC vaccines, and adoptive T cell therapies, are being designed to enhance the immune recognition and destruction of WT1-expressing cancer cells." (PMID 40493404, 2025). "Notably, the crude ethanolic extract of Z. officinale demonstrated greater WT1 downregulation than shogaol, even though shogaol exhibited better cancer prevention properties." (PMID 40022126, 2025). "Notably, the IC20 values of curcuminoids and shogaol exhibited cancer prevention properties and reduced WT1 protein expression, thereby inhibiting cell proliferation." (PMID 40022126, 2025).
cancer (continued). "Necroptosis induction contributes to suppressing therapeutic resistance in cancer stem cells, thus we evaluated whether the identified targets WT1 and FOXA1, which have an impact on stemness by targeting AR, could also play a role in necroptosis activation." (PMID 40399259, 2025). "Additionally, both the Wilms’ tumor gene 1 (WT1) peptide cancer vaccine and the Galinpepimut-S peptide cancer vaccine have yielded promising immune response." (PMID 39789208, 2025). "It remained unclear whether WT1-specific TCRs derived from healthy donors could be mapped to the repertoires of cancer patients." (PMID 39259326, 2025). "Thus, the WT1-specific TCR repertoire has potential as a promising biomarker for response prediction to cancer treatment." (PMID 39259326, 2025). "For many years, how WT1 both promotes and suppresses cancers remained elusive." (PMID 40276932, 2025). "As such, WT1 has been identified as a nearly universal tumor-associated antigen (TAA) overexpressed in numerous solid and hematological cancers, and has been listed as the most interesting cancer antigen for immune therapies." (PMID 39259326, 2025). "Moreover, ADRB1, CCDC28B, MRAP2, SERPINA12, and WT1 were able to effectively distinguish between normal breast tissue and cancer tissue (AUC > 0.6)." (PMID 38676834, 2024). "Interestingly, WT1-expressing cancer stem cells are completely eradicated by the WT1 immune response, which is essential for cancer cure; hence, this uniqueness of WT1 greatly contributes to cancer cure." (PMID 38336778, 2024). "We have used WT1-dendritic cell vaccine (WT1-DC), in which WT1 is recognized by dendritic cells ex vivo, for treatment and have reported successful responses in late-stage cancers that have failed chemotherapy." (PMID 39035592, 2024). "Consequently, WT1 has been identified as one of a potential target antigen for cancer immunotherapy, and had previously been selected as the most promising one of the 75 TAAs." (PMID 39509060, 2024). "Thus, although the data is still limited, WT1 overexpression in TETs provides an opportunity to develop specific cancer vaccines; however, the impact of this therapeutic strategy on the development of autoimmune-related complications is not yet known." (PMID 38966177, 2024). "After multiple cycles of Wilms' tumor antigen 1 (WT1) dendritic cell vaccine therapy and highly activated natural killer (NK) cell therapy, the patient showed a disappearance of ascites and a remarkable reduction of multiple cancers in the whole body." (PMID 38523872, 2024). "This characteristic feature is harvested to develop cancer vaccines against WT1." (PMID 38665761, 2024). "Consequently, studies have been initiated to investigate the possibility of using a WT1 cancer vaccine to treat PDA." (PMID 38665761, 2024). "Finally, further investigation into E7K-tWt1 RNA binding is warranted, given the known RNA binding ability of KTS + WT1 isoforms and their implication in cancer progression." (PMID 38977895, 2024). "Both functions of WT1 as a transcription regulator and a translation regulator may contribute to the pathogenesis of cancer." (PMID 36760714, 2023). "This oral WT1 protein vaccine has clinical applicability because of its potential advantages: high safety, low-cost manufacturing, easy scale-up for massive production, and expectation for good adherence by cancer patients, especially pediatric patients." (PMID 35699757, 2023). "The WT1-derived peptide, WT1-pTj, has displayed significant effects on cancer cells." (PMID 37725261, 2023).